NCF1 (neutrophil cytosolic factor 1)
Description:
Subunit of the phagocyte NADPH oxidase complex that mediates the transfer of electrons from cytosolic NADPH to O2 to produce the superoxide anion (O2(-)). In the activated complex, electrons are first transferred from NADPH to flavin adenine dinucleotide (FAD) and subsequently transferred via two heme molecules to molecular oxygen, producing superoxide through an outer-sphere reaction. Activation of the NADPH oxidase complex is initiated by the assembly of cytosolic subunits of the NADPH oxidase complex with the core NADPH oxidase complex to form a complex at the plasma membrane or phagosomal membrane. This activation process is initiated by phosphorylation dependent binding of the cytosolic NCF1/p47-phox subunit to the C-terminus of CYBA/p22-phox.
Synonyms: NCF-1; NOXO2; SH3PXD1A; p47phox; NCF1A; CGD1; NCF-47K; p47-phox
Tractability: Small molecule: a structure with a bound ligand is known; it has a binding pocket of medium quality. Antibody: UniProt places it where antibodies can reach, with high confidence; its Gene Ontology location is reachable by antibodies, with high confidence.
Gene: Protein-coding gene on chromosome 7 (74,773,975 to 74,789,376, forward strand). Ensembl gene ENSG00000158517.
Subcellular location: Cytoplasm, cytosol; Membrane
Pathways (Reactome):
Signal Transduction: RAC1 GTPase cycle; RAC2 GTPase cycle; RAC3 GTPase cycle; RHO GTPases Activate NADPH Oxidases; VEGFA-VEGFR2 Pathway
Immune System: Cross-presentation of particulate exogenous antigens (phagosomes); ROS and RNS production in phagocytes
Cellular responses to stimuli: Detoxification of Reactive Oxygen Species
Gene Ontology:
Molecular function: phosphatidylinositol binding; phosphatidylinositol-3,4-bisphosphate binding; protein binding; SH3 domain binding; superoxide-generating NAD(P)H oxidase activity; electron transfer activity; superoxide-generating NADPH oxidase activator activity
Biological process: protein targeting to membrane; superoxide anion generation; cellular defense response; innate immune response; respiratory burst; superoxide metabolic process; cellular response to glucose stimulus; cellular response to testosterone stimulus; reactive oxygen species biosynthetic process; reactive oxygen species metabolic process; regulation of respiratory burst involved in inflammatory response
Cellular component: cytoplasmic side of plasma membrane; cytosol; membrane; NADPH oxidase complex; plasma membrane; cytoplasm; phagolysosome; dendrite; neuronal cell body
Genetic constraint (gnomAD): Loss-of-function variants: 6 observed, 19.2 expected, observed/expected ratio (o/e) 0.31, 90% interval 0.17 to 0.62. The synonymous counts are far from expectation, so gnomAD's model fits this gene poorly and the ratio says little. Missense variants: 108 observed, 210.92 expected, observed/expected ratio (o/e) 0.51, 90% interval 0.44 to 0.6. Synonymous variants: 48 observed, 80.14 expected, observed/expected ratio (o/e) 0.6, 90% interval 0.47 to 0.76.
Homologues: Orthologues: chimpanzee NCF1 (99% identical), macaque NCF1 (97% identical), rat Ncf1 (82% identical), guinea pig NCF1 (82% identical), mouse Ncf1 (82% identical), dog NCF1 (80% identical), pig NCF1 (78% identical), tropical clawed frog ncf1 (62% identical), zebrafish ncf1 (55% identical). Paralogues in human: SH3PXD2A (35% identical), SH3PXD2B (35% identical), NOXO1 (21% identical).
Diseases named in the same sentence as NCF1 in open-access papers:
NCF1 is named in the same sentence as 216 diseases in open-access papers, as found by Europe PMC text mining. Sharing a sentence is not in itself a finding about the gene and the disease. The quoted sentences say what the papers report.
chronic granulomatous disease (72 papers, 2006 to 2025). Chronic granulomatous disease (CGD) is a rare primary immunodeficiency, mainly affecting phagocytes, which is characterized by an increased susceptibility to severe and recurrent bacterial and fungal infections, along with the development of granulomas. "p47phox-deficient chronic granulomatous disease (p47-CGD) is a primary immunodeficiency caused by mutations in the neutrophil cytosolic factor 1 (NCF1) gene, resulting in defective NADPH oxidase function in phagocytes." (PMID 38952440, 2024). "The patient reported here underwent hematopoietic stem cell transplantation (HSCT) due to chronic granulomatous disease (CGD) caused by biallelic mutations of the NCF1 gene." (PMID 38003028, 2023). "We identified genetic variations in JAK2, BACH2, and NCF1 that have been associated with autoimmune diseases such as inflammatory bowel disease and chronic granulomatous disease." (PMID 33903979, 2021). "Biallelic loss-of-function variants in NCF1 lead to reactive oxygen species deficiency and chronic granulomatous disease (CGD)." (PMID 33892719, 2021). "We also identified a biallelic loss of NCF1, which indicated autosomal recessive chronic granulomatous disease (CGD)." (PMID 34804071, 2021). "Ncf1 is a prime example of this phenomenon, in which humans that lack the Ncf1 protein will develop chronic granulomatous diseases (CGD) while an allelic variant of Ncf1 (Arg90His) drives a strong association with multiple autoimmune diseases." (PMID 35052516, 2021). "Klatt, Schambach and colleagues generated patient-like p47-ΔGT iPSCs for disease modeling of chronic granulomatous disease and subsequent gene correction of NCF1 (encodes p47phox) using CRISPR/Cas9." (PMID 31543470, 2019). "A sample of alveolar rhabdomyosarcoma and a sample of undifferentiated pleomorphic sarcoma both demonstrated a mutation in NCF1, mutation of which can be associated with chronic granulomatous disease." (PMID 29541442, 2018). "In humans, mutations in genes forming the Nox2 complex (CYBB, CYBA, NCF1,2,4) cause chronic granulomatous disease (CGD), a rare inherited immunodeficiency syndrome." (PMID 30274229, 2018). "A 2-bp GT deletion in exon 2 of the NCF1 gene causes chronic granulomatous disease (CGD) in humans." (PMID 20178640, 2010). "For example, mutations or deletions in NCF1 cause a rare genetic disorder called chronic granulomatous disease (CGD) that is associated with defective ROS production, recurrent infections, and granuloma formation." (PMID 40710296, 2025). "It has been previously shown that patients with hypersensitivity pneumonitis (HP), a rare initial presentation in chronic granulomatous disease (CGD) have mutations in NCF1 and NCF2 genes and are more susceptible to invasive pulmonary A. fumigatus infection." (PMID 37790311, 2023). "For example, chronic granulomatous disease (CGD) is caused by the chimeric form of NCF1 (neutrophil cytosolic factor 1) and its pseudogenes NCF1B (neutrophil cytosolic factor 1B pseudogene) and NCF1C (neutrophil cytosolic factor 1C pseudogene)." (PMID 35012455, 2022). "Homozygous or compound heterozygous mutations in NCF1 cause autosomal recessive chronic granulomatous disease (CGD) (OMIM: 233700)." (PMID 33499153, 2021). "A deficiency of the Ncf1 gene was first identified to be one of the genetic causative factors for development of chronic granulomatous disease (CGD)." (PMID 34970267, 2021). "The NOXO1-CYBA interaction is similarly disrupted by the chronic granulomatous disease (CGD)-associated P156Q mutation in the CYBA motif 155-PPPRP-159, suggesting a similar binding mechanism as seen for the NCF1-CYBA interaction." (PMID 41463297, 2025). "An example is the locus coding for neutrophil cytosolic factor 1 (NCF1), a gene linked to chronic granulomatous disease." (PMID 41425600, 2025).
chronic granulomatous disease (continued). "In chronic granulomatous disease, experimental alignment of the modified Kozak sequence in NCF1 to the Kozak consensus sequence was shown to abolish haploinsufficiency." (PMID 39596509, 2024). "Mutations in the five structural genes (NCF1, NCF2, NCF4, CYBA, CYBB) are associated with chronic granulomatous disease (CGD), a condition characterized by impaired production of reactive oxygen species (ROS)." (PMID 37533075, 2023). "NCF1 codes for p47phox, a critical subunit in the assembly of NADPH oxidase (NOX); homozygous deficiency accounts for 20% of patients with chronic granulomatous disease, a disorder associated with repeated infections due to an inability to kill bacteria." (PMID 22319454, 2012). "NCF1 is one of the genes responsible for the chronic granulomatous disease (CGD) and also contributes to autoimmunity." (PMID 18047649, 2007). "Finally, we and others observed suppressed murine Treg expansion in Ncf1*/* mutant chronic granulomatous disease (CGD) mice with anti-CD3ε/CD28 stimulation, which was reestablished during Treg polarization with robust TGFβ signaling." (PMID 41300507, 2025). "Studies of mutations causing human chronic granulomatous disease show that mutations in NCF1, CYBB, CYBA, or NCF2 lead to a complete lack of function of the NOX complex." (PMID 17897462, 2007). "Researching on mutations causing human chronic granulomatous disease showed that mutations in NCF1 and CYBB could result in a complete lack of function of the NOX2 complex." (PMID 37087463, 2023). "Patient P55 was found to have rare exonic variants in both NCF1 (c.269G>A; p.R90H; HGNC:7660) and NCF2 (c.812A>G; p.Lys271Arg; HGNC:7661), which are primarily linked to chronic granulomatous disease (CGD, OMIM 233700)." (PMID 35743704, 2022). "Chronic granulomatous disease is an immunodeficiency disease caused by defects in any of the five structural components of the NOX enzyme, i.e., X-linked recessive mutations in Cybb (gp91phox), or autosomal recessive mutations in Cyba (p22phox), Ncf1 (p47phox), Ncf2 (p67phox), or Ncf4 (p40phox)." (PMID 33842458, 2021). "In particular, Nox2 oxidase function deficiency in phagocytes due to genetic variants (CYBB, CYBA, NCF1, NCF2, and NCF4) has been recognized as a direct cause of chronic granulomatous disease (CGD), an inherited immune disorder." (PMID 29867559, 2018). "Independently, many groups worldwide have associated the non-synonymous single nucleotide polymorphism (SNP) NCF1-339 (rs201802880) with multiple autoimmune diseases, such as systemic lupus erythematosus (SLE), chronic granulomatous disease (CGD), and rheumatoid arthritis." (PMID 36448060, 2022). "Chronic granulomatous Disease (CGD) is a rare innate immunodeficiency disorder caused by mutations in one of the six genes (CYBA, CYBB, NCF1, NCF2, NCF4, and CYBC1/EROS) encoding the superoxide-producing nicotinamide adenine dinucleotide phosphate (NADPH)—oxidase complex in phagocytes." (PMID 33746979, 2021). "The diagnoses clustered within the phagocyte diseases consisted of autosomal recessive chronic granulomatous disease (AR-CGD) (n=2/5; 40%), G6PD deficiency (n=2/5;40%) and MKL1 deficiency (n=1/5; 20%), based on pathogenic variants in NCF1, G6PD and MKL1, respectively." (PMID 34992599, 2021). "Up to date, the commonly used Ncf1 knockout mouse was originally generated using 129 ES cells, backcrossed to C57BL/6 mice, and used as a model of chronic granulomatous disease (CGD)." (PMID 26528554, 2015). "Mutations preventing the tandemization of SH3 domains within NCF1 or destroying the tSH3-binding motif in the partner CYBA lead to a lack of functional NADPH oxidase and are implicated in Chronic Granulomatous Disease (CGD), a severe immune deficiency." (PMID 41463297, 2025).
chronic granulomatous disease (continued). "Ncf1-deficient mice have a syndrome similar to a human disorder arising from Ncf1 mutations (chronic granulomatous disease; CGD) that can be attributed primarily to a lack of effective antimicrobial killing due to absence of NADPH oxidase function in phagocytes." (PMID 21253614, 2011).
Arthritis (48 papers, 2005 to 2026). Inflammation of a joint. "More severe arthritis, earlier onset, enhanced cartilage destruction, and higher levels of anti-collagen antibodies have also been observed in a collagen-induced arthritis Ncf1 mutated mouse model." (PMID 40227295, 2025). "NCF1 encodes neutrophil cytosolic factor 1, which was shown to regulate T cell activation in autoimmunce diseases like arthritis." (PMID 40179341, 2025). "The arthritis-modulating effect of the SNP in NCF1 is linked to an altered capacity of the NOX2 complex to generate ROS." (PMID 39430588, 2024). "We found that the redox insensitivity of LAT affects its localization and phosphorylation, leading to changes in T cell selection, susceptibility to inflammation, and development of arthritis, an effect reversed by the NCF1 mutation." (PMID 38671946, 2024). "Mutations in both Ncf1 and Ncf4 affect development of arthritis in experimental models of RA, but the different regulatory pathways mediated by NOX2-derived reactive oxygen species (ROS) have not yet been clarified." (PMID 38547647, 2024). "A single-nucleotide polymorphism (SNP) in NCF1 has been identified as a modulator of arthritis severity, establishing NCF1 as a genetic factor associated with RA, as observed in rodent models of arthritis." (PMID 39430588, 2024). "The data showed that we successfully established the mCAIA with chronic phase with severe arthritis in Ncf1 mutated mice." (PMID 35551534, 2022). "Using a mouse carrying a natural mutation in the Ncf1 gene (Ncf1m1J), the importance of NCF1 has been revealed for various autoimmune diseases, including arthritis, experimental autoimmune encephalomyelitis (EAE), SLE, psoriasis, etc.." (PMID 35788118, 2022). "In conclusion, the new human-mimicking mouse model has strong T cell tolerance to COL2, which can be broken by deficiency of Fcgr2b or Ncf1, allowing activation of autoreactive T cells and development of arthritis." (PMID 35963953, 2022). "In comparison, the transgenic model showed less pronounced protection against arthritis together with the Ncf1 mutation." (PMID 35963953, 2022). "Mutant Ncf1 caused a reduction in intracellular ROS, which resulted in more severe collagen-induced arthritis." (PMID 35740050, 2022). "The Ncf1m1j/m1j mutations decreasing NCF1 function, leading to a diminished induction of ROS, are causative alleles for both arthritis and lupus." (PMID 35963953, 2022). "RA is an autoimmune disease, and naturally occurring deficiencies in the Ncf1 locus causing a reduced oxidative burst led to enhanced autoimmunity and arthritis." (PMID 34829531, 2021). "The first finding was the positionally cloning of the neutrophil cytosolic factor 1 (Ncf1) gene to be associated with arthritis in a rat model." (PMID 34970267, 2021). "It has been shown that in mice, a superoxide defect caused by mutations in the NCF1 gene was found to cause arthritis and lupus." (PMID 34831240, 2021). "We introgressed single (Clec4b) or double (Clec4b/Ncf1) alleles derived from arthritis-resistant E3 rat strain into the arthritis-susceptible DA strain." (PMID 35052516, 2021). "A collagen-induced arthritis model generated by Ncf1 mutation in mice has more severe symptoms, higher anti-CII IgG levels, and stronger Th1 responses than wild-type mice, which can be reversed by restoration of functional Ncf1 solely in macrophages." (PMID 33717180, 2021). "Mixture of these new “adjuvants” with natural CII triggers more severe arthritis and stronger autoantibody responses in Ncf1-mutated mice, in which macrophage ROS also plays a central role." (PMID 33717180, 2021). "NCF1 knockout causes increased T-cell activity in mice, resulting in arthritis and encephalomyelitis phenotypes." (PMID 34009325, 2021). "We previously showed that a single nucleotide polymorphism in Ncf1, resulting in loss-of-function amino acid substitution, led to an increased risk of developing arthritis." (PMID 32276661, 2020).
Arthritis (continued). "In the mCAIA model, the presence of the Ncf1 mutation has a more dramatic effect and enhanced the development of arthritis, allowing it to develop into a chronic relapsing disease." (PMID 32448385, 2020). "Superoxide defect by mutations in Ncf1 gene was subsequently shown to cause arthritis and lupus in mice, and in humans." (PMID 32276661, 2020). "All mice had a mutation in the Ncf1 gene, which enhances arthritis susceptibility and allows for the development of arthritis in MMC mice." (PMID 29367624, 2018). "The arthritis-protective congenic rat with an E3-derived Ncf1 on a susceptible DA background showed an increased oxidative-burst response." (PMID 27736747, 2016). "This discovery in rats was strengthened by the finding that a spontaneous mutation in the mouse Ncf1 gene, which reduces Ncf1 expression and produces an undetectable ROS response, gives rise to enhanced arthritis." (PMID 27736747, 2016). "Dark Agouti (DA) rats develop an increased susceptibility to arthritis due to a genetic polymorphism for ncf1 encoding p47phox." (PMID 23658840, 2013). "A polymorphism of the Ncf1 gene regulates the severity of arthritis in rats and mice, and has been shown to be caused by NADPH oxidase deficiency." (PMID 21159208, 2010). "This is highlighted by reports showing that mutant mice with reduced capacity to produce ROS due to a polymorphism in the neutrophil cytosolic factor 1 (Ncf1) are more prone to severe arthritis." (PMID 17890113, 2007). "By studying animal models, reduced capacity of the NADPH-oxidase (NOX) complex, caused by a single nucleotide polymorphism (SNP) in one of its components (the NCF1 gene), has been found to increase severity of arthritis." (PMID 17897462, 2007). "We now show that the Ncf-1 allele that enhances oxidative burst and protects against arthritis is operating through an IFN-β-associated pathway, whereas the arthritis-driving allele operates through an IFN-γ-associated pathway." (PMID 17490473, 2007). "These rats carry different alleles of the Ncf1 gene, and differ dramatically in arthritis severity; the DA rat is highly susceptible and the congenic DA.Ncf1E3 is almost completely resistant to arthritis." (PMID 17490473, 2007). "By positional cloning in rat models of arthritis, a polymorphism of Ncf1 was found to regulate arthritis severity." (PMID 17490473, 2007). "This analysis was included to study the importance of the selected genes for the difference in arthritis susceptibility caused by different Ncf1 alleles, and thus also NADPH oxidase functionality in PIA compared with phytol treatment." (PMID 17490473, 2007). "Interestingly, the enhancement of arthritis induced by LPS in the CAIA model is counteracted by the Ncf1 mutation, but is more severe if enhanced by mannan." (PMID 35551534, 2022). "Deficiency in local and systemic ROS production caused by defective NOX2 hence may underlie our observation that more severe arthritis was induced in Ncf1-/- mice." (PMID 34557202, 2021). "Other free radicals, namely reactive nitrogen species, also contribute to arthritis pathogenesis in Ncf1-mutated mice, and may counteract the effects of ROS." (PMID 33717180, 2021). "However, Ncf1 deficiency leads to slightly higher arthritis susceptibility in the antibody phase of arthritis." (PMID 32448385, 2020). "Similarly, our laboratory used a serum-induced arthritis mouse model to identify cathepsin B as one of the major proteases in the pro-IL-1β processing in the ROS-deficient Ncf1-/- mice." (PMID 29228045, 2017). "Animals bearing Ncf1 variants associated with low burst capacity exhibit enhanced arthritis susceptibility and severity in murine models of collagen- and pristane-induced arthritis." (PMID 26346244, 2015). "However, introducing a point mutation in the Ncf1 gene (yielding the strain B10.DR4.Ncf1*/*) led to susceptibility to arthritis." (PMID 23116329, 2012).